PLAC8 (placenta associated 8)
Diseases named in the same sentence as PLAC8 in open-access papers (continued):
Sharing a sentence is not in itself a finding about the gene and the disease.
preeclampsia (4 papers, 2018 to 2025). Preeclampsia is a hypertensive disorder of pregnancy that is characterized by new-onset hypertension with proteinuria presenting after 20 weeks of gestation, and depending on mild or severe forms may initially present with severe headache, visual disturbances, and hyperreflexia. "Our results suggest that pregestational obesity is associated with SPE and PLAC8 gene, and protein expression are significantly higher in women with preeclampsia than in women with normal pregnancy." (PMID 35252239, 2022). "The hypoxic placenta in preeclampsia maintains low oxygen levels and, as consequence, causes high PLAC8 expression throughout pregnancy." (PMID 35252239, 2022). "This elevated PLAC8 expression could potentially function as an interplay molecule between signaling pathways, forming a molecular bridge connecting placental hypoxia to downstream mediators associated with preeclampsia." (PMID 40508180, 2025). "This suggests potential implications of PLAC8 overexpression in placental disorders, like preeclampsia, and other trophoblastic diseases, such as hyperinvasive placentas acretas, incretas, and percretas." (PMID 40508180, 2025). "This suggests that O2 concentration and TGF-β1 synergistically regulate PLAC8 expression, potentially linking placental hypoxia to downstream mediators of preeclampsia." (PMID 40508180, 2025). "In the present study, a high level of gene and protein expression of PLAC8 at the end of pregnancy was observed in women affected by preeclampsia compared to healthy pregnant women in whom it seems to decrease as the pregnancy progresses." (PMID 35252239, 2022). "Additionally, epigenetic mechanisms of regulation of PLAC8 expression in preeclampsia should also be explored." (PMID 35252239, 2022). "Both the gene expression of PLAC8 in PHCT isolated from placental villi and in term placental protein expression showed significantly higher elevations in preeclampsia samples than in the HP samples (p < 0.05)." (PMID 35252239, 2022). "Although a direct experimental link to preeclampsia was not established in this study, previous reports have shown increased PLAC8 expression in placental tissue from preeclamptic pregnancies." (PMID 40508180, 2025). "In a previous study published by our working group, as well as by other groups, it was observed that PLAC8 expression is increased in EVTs from preeclamptic placentas compared to those in placentas without preeclampsia." (PMID 40508180, 2025). "High expression of Plac8 is involved in adipogenesis, brown fat differentiation, and body weight control through interaction with C/EBPβ, which in turn transactivates the C/EBP site in the Lep gene, stimulating its transcription and its potential proinflammatory activity in preeclampsia." (PMID 35252239, 2022). "However, the current widely accepted etiology of preeclampsia, defects in EVT differentiation and the subsequent shallow invasion of iEVTs in the decidua, would predict a decrease in the expression of PLAC8, which is opposite to the results found in this study." (PMID 29361555, 2018).
viral infection (4 papers, 2021 to 2025). "Cytotoxic effector genes (GZMA, GZMB, ID2, and PLAC8) were enriched in Δ382 SARS-CoV-2 infected patients, coupled with high plasma levels of IFN-γ, TNF-α, and IL-2 during the acute phase of virus infection." (PMID 34716845, 2022). "Consistent with the putative role of PLAC8 in viral infection, we observed that these two cell types also show the highest PLAC8 expression levels and a high percentage of ACE2 and PLAC8 double‐positive cells." (PMID 36124427, 2022).
diabetes (3 papers, 2022 to 2023). "There are emerging reports linking PLAC8 to disease progression, including cancer and diabetes, although specific mechanisms are poorly defined." (PMID 37759443, 2023). "The downregulated genes in cluster 9 in the diabetes group on day 1 including Arg1, Cxcl3, Plac8, Saa3 were enriched in response to external biotic stimulus, response to other organism, response to biotic stimulus, defence response (Supplementary 11)." (PMID 36445632, 2023).
Hyperglycemia (3 papers, 2018 to 2021). An increased concentration of glucose in the blood. "PLAC8 was found to be highly expressed in neonatal cells exposed to GD and expression of PLAC8 was correlated with maternal hyperglycemia." (PMID 32028606, 2020). "Overexpression of placenta-specific-8 (PLAC8) in GDM-ECFCs was attributable to hypomethylation at regulatory regions and correlated with the degree of maternal hyperglycemia." (PMID 30463313, 2018).
liver cancer (3 papers, 2005 to 2025). An epithelial or non-epithelial malignant neoplasm that arises from the liver. "For instance, exosomes derived from tumor-associated fibroblasts contain mirtron hsa-mir-1228–3p, which enhances liver cancer cell resistance to sorafenib by directly targeting placenta-associated 8 (PLAC8)." (PMID 40861257, 2025). "In another research, it was shown that overexpression of PLAC8 decreased the activity of liver cancer cells via inhibiting the Wnt/β-Catenin signaling pathway." (PMID 35497881, 2022). "In liver cancer, the abnormal expression of PLAC8 can activate the Wnt/β-Catenin pathway and promote the malignant proliferation of liver cancer cells." (PMID 35497881, 2022). "The gene of unknown function, PLAC8 appears to have a role in Liver cancer, and based on our HMM modeling might have a domain similar to part of the crystal structure of 1P59." (PMID 15826317, 2005).
acute myeloid leukemia (2 papers, 2018). Acute myeloid leukemia (AML) is a group of neoplasms arising from precursor cells committed to the myeloid cell-line differentiation. "Subsequently, PLAC8 has been found to play important roles during cell apoptosis and proliferation as a c-Myc-repressed target, and during the differentiation of acute myeloid leukemia cells." (PMID 29361555, 2018).
acute myocardial infarction (2 papers, 2013 to 2025). Necrosis of the myocardium, as a result of interruption of the blood supply to the area. "In the present study, we were interested in the role of PLAC8 in myocardial infarction-induced myocardial injury and its intrinsic mechanism." (PMID 40471391, 2025). "In this study, it was found that overexpression of PLAC8 rescued the high expression of these markers, reversed the progression of myocardial infarction to heart failure, reduced cardiomyocyte injury, and lowered the expression of the inflammatory markers TNF-α and IL-1β in serum." (PMID 40471391, 2025). "The GSE161151 database sample is an 8-week C57BL/6 mouse model of myocardial ischemia-reperfusion injury (45 min of ischemia and 24 h of reperfusion) found that the expression of PLAC8 in the myocardial infarction zone samples showed a significant downward trend." (PMID 40471391, 2025).
adenomyosis (2 papers, 2020 to 2021). The growth of endometrial tissue inside the muscular wall of the uterine corpus. "PLAC8 mRNA is also increased in the myometrium of adenomyosis patients, indicating the role of the immune response in the myometrium of women with adenomyosis." (PMID 34627411, 2021). "Possible target genes, including cadherin 3(CDH3), sodium channelβ-subunit 4 (SCN4B), and placenta-specific protein 8 (PLAC8), which are involved in cell adhesion, muscle contraction and immune response in the myometrium of adenomyosis patients were also validated." (PMID 32719721, 2020).
adult-onset Still disease (2 papers, 2021 to 2024). A rare inflammatory multisystem disorder characterized clinically by fever of unknown origin, arthralgia or arthritis, hyperleucocytosis, and typical skin rash. "For example, PLAC8 suppresses the production of the pro-inflammatory cytokines, IL-1b and IL-18, via enhancement of autophagy in adult-onset Still’s disease." (PMID 34627411, 2021). "In addition to cancer, PLAC8 also enhances autophagy in adult-onset Still’s disease and promotes trophoblast cells autophagy though regulating autophagy-related markers, including LC3B I/II, ATG12 and Beclin-1." (PMID 34627411, 2021).
cervical cancer (2 papers, 2020 to 2024). A primary or metastatic malignant neoplasm involving the cervix. "In our study, we found that the expression of PLAC8 was increased by hypomethylation, demonstrating that PLAC8 may function as an initiator of cervical cancer proliferation." (PMID 32368784, 2020).
clear cell renal cell carcinoma (2 papers, 2021 to 2023). "Enhanced sensitivity to cisplatin treatment following silencing of PLAC8 in clear cell renal cell carcinoma cells suggests a potential therapeutic target of PLAC8." (PMID 34627411, 2021). "And RNA sequencing data of clear cell renal cell carcinoma has shown that PLAC8 is mainly involved in immunity-related pathways." (PMID 34627411, 2021). "PLAC8 promotes trophoblast cell, non-small cell lung cancer cell, and clear cell renal cell carcinoma invasion and migration." (PMID 34627411, 2021).
influenza infection (2 papers, 2020 to 2025). "Other studies identified Plac8 as a critical factor for the establishment of memory CD8+ T cells after influenza infection, which was also highly expressed in H1N1-induced TRM in our study, but not in the vaccine-induced TRM58." (PMID 40240341, 2025). "On the contrary, Plac8 was important for optimal establishment of virus-specific effector CD8 T cells in response to influenza infection." (PMID 32639988, 2020). "Surprisingly, Plac8 was important for the establishment of effector influenza-specific CD8 T cells through a T cell-intrinsic manner when utilizing a mixed bone marrow chimera model and an OT-I T cell adoptive transfer model." (PMID 32639988, 2020). "Plac8 protein is expressed by other immune and stromal cells, such as macrophages and lung epithelial cells, that participate in the immune response to influenza, and can indirectly influence the influenza-specific CD8 T cell response." (PMID 32639988, 2020). "In addition, we determined that global Plac8 expression promotes the establishment of memory CD8 T cells following influenza infection, which may promote efficacy rates in the current influenza vaccines." (PMID 32639988, 2020). "Therefore, it will be important to determine Plac8’s impact on global immune cell function and CD8 T cell-specific functions during influenza infection." (PMID 32639988, 2020). "However, when comparing the NP-specific CD8 T cell response in the complete WT versus Plac8-/- influenza mouse model, Plac8 was important for the establishment of memory, but not effector, CD8 T cells." (PMID 32639988, 2020).
renal carcinoma (2 papers, 2022 to 2023). A carcinoma arising from the epithelium of the renal parenchyma or the renal pelvis. "In vitro experiments demonstrated a significant reduction in the proliferation, invasion and migration of renal cancer cells following the knockdown of PLAC8." (PMID 38023190, 2023). "Nevertheless, the precise biological function of PLAC8 in renal cancer remains unknown." (PMID 38023190, 2023).
rheumatoid arthritis (2 papers, 2022 to 2025). A chronic, systemic autoimmune disorder characterized by inflammation in the synovial membranes and articular surfaces. "In chronic inflammation, rheumatoid arthritis, and autoimmune diseases, PLAC8 expression is often elevated, potentially exacerbating or modulating the inflammatory response by influencing the function of immune cells and the levels of secreted cytokines." (PMID 39917301, 2025).
acute peritonitis (1 paper, 2023). "We did not detect significant differences in bacterial burden between WT and miR-223−/− mice despite Plac8 being acknowledged to have antibacterial properties, as revealed by the increased bacterial burden in its absence following K. pneumoniae-induced acute peritonitis." (PMID 36980300, 2023).
asthma (1 paper, 2022). "In our Nb infection model, lung cells and a fraction of proximal clustering MLN cells also express genes associated with asthma or involved in pathways targeted by drugs for asthma treatment like Cysltr1, Plac8, or Adam8." (PMID 35950748, 2022).
bone tumors (1 paper, 2013). "Since there is a possibility that one week culturing may affect gene expression of PC3-GFP, expression levels of GFP, RBP4 and PLAC8 in bone tumors were examined by immunohistochemical staining." (PMID 23708710, 2013). "Immunohistochemical staining of GFP, RBP4 and PLAC8 showed that bone tumors formed by injection of the mixture of PC3-GFP/PC3-mock or PC3-GFP/PC3-OPG, contained GFP-positive cells and the expression levels of both RBP4 and PLAC8 were increased in tumor cells from PC3-GFP/PC3-OPG-injected mice." (PMID 23708710, 2013).
breast tumour (1 paper, 2021). "PLAC8 knockdown in animal models abrogated breast tumour growth supporting an oncogenic role." (PMID 34117724, 2021).
chlamydia (1 paper, 2017). "In genital chlamydia models, it has been shown that the enhancement of TNFα is also required for achieving protection against chlamydia and mechanisms that are nearly IFNγ independent but dependent on Plac8 and likely on T cell degranulation exist as well." (PMID 28678871, 2017).
colitis (1 paper, 2020). Inflammation of the colon. "Because we saw an increase in CD4 T cell IFNγ production 24 h-post IL-12 stimulation in vitro, and the T cell transfer model of colitis induces chronic inflammation over several weeks, we hypothesized that Plac8’s impact on CD4 T cell IFNγ may be limited to models of acute inflammation." (PMID 32639988, 2020). "Despite Plac8’s regulation of IFNγ production by CD4 T cells in vitro, Plac8 ablation did not apparently alter T cell effector function in a T cell transfer model of colitis." (PMID 32639988, 2020). "Interestingly, however, Plac8-/- CD4 T cells did not induce enhanced morbidity compared to Plac8+/+ CD4 T cells in a T cell transfer model of colitis in which Th1 cells are important mediators of disease." (PMID 32639988, 2020). "It is also possible that Plac8’s effect on CD4 T cell IFNγ production occurs transiently, and the magnitude of the enhancement of the IFNγ response in Plac8-/- T cells may not be large enough to manifest during a model of chronic inflammation such as this colitis model." (PMID 32639988, 2020). "While Plac8 significantly suppressed IFNγ production in IL-12 stimulated CD4 T cells in vitro, this phenotype was not captured in either a T cell transfer model of colitis or following Citrobacter rodentium infection." (PMID 32639988, 2020).
gallbladder carcinoma (1 paper, 2021). "PLAC8 overexpression decreases sensitivity to gemcitabine and oxaliplatin in gallbladder carcinoma cells." (PMID 34627411, 2021).
gestational diabetes (1 paper, 2023). Carbohydrate intolerance first diagnosed during pregnancy. "However, there is a paucity of understanding of the role of PLAC8 expression in endothelial progenitor cells, which appears to be limited to reported upregulation in ECFCs isolated from neonates exposed to gestational diabetes, inhibition of which led to an improved proliferation and senescence." (PMID 37759443, 2023).
kidney cancer (1 paper, 2023). Primary or metastatic malignant neoplasm involving the kidney. "The results of the EdU assay demonstrated that the DNA replication activity of kidney cancer cells was significantly reduced after the knockdown of PLAC8." (PMID 38023190, 2023).
leukopenia (1 paper, 2024). "However, it is known from single cell sequencing studies that both PLAC8 and PLA2G7 are expressed across a range of different white cell types, which would mitigate the effect of a selective leukopenia." (PMID 38592057, 2024).
lung adenocarcinoma (1 paper, 2021). A carcinoma that arises from the lung and is characterized by the presence of malignant glandular epithelial cells. "Overexpression of PLAC8 significantly decreases the sensitivity of lung adenocarcinoma to gefitinib." (PMID 34627411, 2021). "Additionally, PLAC8 regulates the expression of POU5F1, thus increasing stemness during lung adenocarcinoma cell resistance to radiotherapy." (PMID 34627411, 2021).
melanoma (1 paper, 2025). A malignant, usually aggressive tumor composed of atypical, neoplastic melanocytes. "Notably, STAT1 was involved exclusively in Stage 4–specific synergistic relationships within the melanoma network, whereas TNFSF14, STK17B, SAMD3, PLAC8, and LYN were all Stage 1–specific synergistic genes that synergized with FENDRR." (PMID 40728857, 2025).
metastatic tumor (1 paper, 2021). "We also found that examined PLAC8 expression in the tissues of primary tissue and metastatic patients tumor, who were diagnosed with distant metastasis after receiving adjuvant tamoxifen treatment, PLAC8 expression was higher in metastatic tumor compared with their primary tissues." (PMID 33611659, 2021).
multiple sclerosis (1 paper, 2023). A progressive autoimmune disorder affecting the central nervous system resulting in demyelination. "Coexpression of Plac8 and Cxcr4 is found in circulating monocytes and monocyte-derived antigen-presenting cells in an experimental model of multiple sclerosis, suggesting chronic inflammation may be required for the miR-181/Plac8/Cxcr4 axis to be activated." (PMID 36821386, 2023).
non-small cell lung carcinoma (1 paper, 2021). A group of at least three distinct histological types of lung cancer, including non-small cell squamous cell carcinoma, adenocarcinoma, and large cell carcinoma. "In non-small cell lung cancer, overexpression of PLAC8 in parental cells markedly decreases osimertinib sensitivity." (PMID 34627411, 2021). "In non-small cell lung cancer, PLAC8 promotes the levels of ALDH1A1 which is a putative marker for CSCs in numerous types of tumors." (PMID 34627411, 2021).
septic arthritis (1 paper, 2024). "Interestingly, there was significant upregulation of PLAC8 in septic arthritis compared to experimentally induced non-septic synovitis, which is consistent with the behavior of this mRNA transcript within the SeptiCyte Lab panel." (PMID 39057983, 2024).
Shock (1 paper, 2024). The state in which profound and widespread reduction of effective tissue perfusion leads first to reversible, and then if prolonged, to irreversible cellular injury. "Because promyelocytes express PLAC8 and PMNs CEACAM4, and potentially sustain high levels of PLAC8, the expression of these genes may be expected to not increase further with disease severity, as in septic shock, as a result of elevated precursor counts." (PMID 39434093, 2024).
triple-negative breast carcinoma (1 paper, 2025). An invasive breast carcinoma which is negative for expression of estrogen receptor (ER), progesterone receptor (PR), and human epidermal growth factor receptor 2 (HER2). "In triple-negative breast cancer, placenta-specific 8 (PLAC8) stabilizes PD-L1 through UFMylation, thereby suppressing immune cell activity." (PMID 41179291, 2025).